E2F6 (E2F transcription factor 6)
Diseases named in the same sentence as E2F6 in open-access papers (continued):
Sharing a sentence is not in itself a finding about the gene and the disease.
infection (3 papers, 2016 to 2023). The state of being infected such as from the introduction of a foreign agent such as serum, vaccine, antigenic substance or organism. "Human papillomavirus type 16 E7 (HPV E7) and adenoviral E1A protein can interact with E2F6 to inactivate the transcriptional repression activity of E2F6 and subvert the critical cellular defense, but it is unclear whether E2F6 plays a role in the infection of PEDV." (PMID 36406089, 2022).
vasculopathy (1 paper, 2020). "Thus, our identified DEGs (RRM2, APC, CHEK1, E2F6, TYMS, E2F7, and CDK6) from the cluster 2 subnetwork are highly related to and consistent with the members of the signaling pathways associated with the immune system, apoptosis, the cell cycle, and vasculopathy." (PMID 32426333, 2020).
E2F6 also shares sentences with these, for which no sentence is quoted: bladder cancer (3 papers); Allergy (2); breast tumor (2); adenocarcinoma (1); Down syndrome (1); esophageal squamous cell carcinoma (1); gynecological cancers (1); head and neck cancer (1); Hydrocephalus (1); lung diseases (1); Malignant Brain Tumor (1); metastatic cancers (1); neuroblastoma (1); prostate (1); sarcopenia (1); skeletal system disease (1); squamous cell lung carcinoma (1); thalassemia (1).